MTOR (mechanistic target of rapamycin kinase)
Diseases named in the same sentence as MTOR in open-access papers (continued):
Sharing a sentence is not in itself a finding about the gene and the disease.
tumor (continued). "Evidence of an increased rate of autophagy flux, characterized by the conversion of LC3 I to LC3 II, and elevated PPARγ expression, in tandem with weak phosphorylation of mTOR and S6K1, supports the hypothesis that hispidulin can modulate autophagy to suppress tumor progression." (PMID 39860214, 2025). "However, we also observed several druggable pathway alterations in the tumor‐informed ctDNA group, such as ERBB2, MMR, and mTOR signaling, suggesting that alternative strategies beyond immunotherapy might be considered." (PMID 41287887, 2025). "Studies show that upon activation of mTOR, the downstream S6K can phosphorylate insulin receptor substrate 1 (IRS-1), reducing the activity of PI3K and, through negative feedback, attenuating the activity of the PI3K/Akt/mTOR pathway, thereby inhibiting tumor cell activity." (PMID 40704062, 2025). "Of note, a dual inhibitor of bromodomain-containing protein 4 (BRD4) and PI3K-Akt-mTOR, SF2523 blocked Akt-mTOR activation and downregulated MYC and Bcl2 expression in the CS cell line SW1353 and in vivo strongly impaired its subcutaneous tumor growth in immunodeficient mice." (PMID 40004005, 2025). "Therefore, it is evident that targeting inhibition of MCT1, mTOR signaling and activation of TLR8 signaling in tumor tissues enriched with Treg cells may contribute to the improvement of immunotherapy efficacy of OC." (PMID 40045411, 2025). "Future investigations should explore potential interactions with key oncogenic pathways in PCa, such as androgen receptor signaling, PI3K/AKT/mTOR pathway, or Wnt/β-catenin signaling, which could provide deeper insights into how BAIAP2L2 influences tumor cell behavior." (PMID 40356901, 2025). "In addition, HIF-1α may also interact with other oncogenic pathways, such as PI3K/AKT/mTOR and RAS/MAPK, thereby amplifying tumor progression." (PMID 39781344, 2025). "Ketogenic diets mimic glucose starvation conditions, which inhibit tumor growth by modulating multiple signaling pathways, such as the phosphoinositide 3-kinase (PI3K)/protein kinase B (Akt) pathway, AMP-activated protein kinase (AMPK) pathway and mTOR pathway." (PMID 38835066, 2024). "So far, no positive effect on tumor progression and overall survival could be achieved for mTOR inhibitors as immunosuppression in recurrent HCC after liver transplantation." (PMID 39001504, 2024). "To determine whether upregulated PEPCK1 enhances mTOR/TOR signaling and thus promotes tumor growth under HDS conditions, we assessed mTOR/TOR signaling activity using pS6 antibody, a specific antibody against phosphorylated Ribosomal protein S6 (RpS6), in tumor cells." (PMID 39261338, 2024). "The protein encoded by the mammalian lethal with SEC13 protein 8 (MLST8) gene, also known as G protein beta subunit-like (GBL), promotes tumor cell growth and development by regulating mTOR (mechanistic target of rapamycin) signaling and thus does not significantly affect normal cell growth." (PMID 39170695, 2024). "Additionally, as a regulatory hub for multiple signaling pathways, mTOR could also participate in the regulation of PI3K/AKT signaling pathways, reflecting the intricate connections among tumor signaling pathways." (PMID 38268030, 2024). "Thus, bispecific targeting of mTOR and STAT3 could support increased BSV-induced infiltration of CD8+T cells into the tumor region more significantly than the oncolytic virus treatment itself." (PMID 38886756, 2024).
tumor (continued). "The combination of PI3K/mTOR inhibitors with PD‐1 blockade effectively reinvigorated the exhausted T‐cell population, reinstating their effector function and leading to clonal hyper‐expansion of a cytotoxic CD8+ Teff population, ultimately resulting in partial or complete tumour responses." (PMID 38711203, 2024). "Notably, patients in clusters 1 and 2 exhibited enhanced responses to ICIs, with cluster 1 demonstrating a poorer survival rate compared to cluster 2, likely due to the tumor microenvironment favoring pro-tumor immunity involving TNFA, PI3K/AKT/MTOR, and TGFβ signaling pathways." (PMID 39445012, 2024). "However, we cannot rule out that the mechanism of action on different cell types (e.g. hepatic, pancreatic, tumor, muscles) of a pan‐PI3K/mTOR inhibitor leads to fundamentally different outcomes with respect to the effect on biochemical carbon homeostasis when compared to single‐node PAM inhibitors." (PMID 39092562, 2024). "This brings us to an important consideration: while the early treatment of TSC-related tumours is clearly advantageous, mTOR inhibitors may not address the full spectrum of TSC neurodevelopmental challenges." (PMID 39518472, 2024). "In addition, a negative correlation between mTOR gene expression and p62 protein levels in tumor tissues (R=-0.758, p<0.001) were observed." (PMID 38164366, 2024). "Therefore, the interplay between mTOR and YAP transcriptional regulation may thus play an important role in tumor progression and the drug response in HER2-positive GC." (PMID 38782859, 2024). "Furthermore, we discovered that insulin or IGF-1 binds to specific receptors on tumor cell membranes to regulate tumor growth and glucose metabolism by activating the PI3K/AKT/mTOR pathway in EC, meanwhile metformin can reduce plasma IGF-1 concentration thereby exerting anticancer activity." (PMID 38577616, 2024). "KDs could also modulate immune function as they were found to enhance the innate and adaptive immune responses against tumor cells, including cytolysis mediated by tumor-reactive CD8+ T cells, and to influence the activity of mammalian target of rapamycin (mTOR), which regulates the immune function." (PMID 39064705, 2024). "Besides, the Western blot results were consistent with the prediction data, which meant that in the MAD2L2 over-expressed OVCA cells, mTOR might upregulate SLC7A11 to restrain ferroptosis and promote tumor growth in OVCA cells." (PMID 38167649, 2024). "In addition, in different tumor cells, β-caryophyllene oxide can simultaneously target PI3K/AKT/mTOR/S6K1 and MAPK signaling pathways, inhibit the proliferation of related tumor cells and induce the apoptosis of tumor cells by activating caspase-3 and releasing cytochrome c." (PMID 38611927, 2024). "Additionally, a negative correlation between mTOR gene and p62 protein levels in tumor tissues is observable, indicating inhibition of autophagy in high levels of mTOR expression." (PMID 38164366, 2024). "We previously demonstrated the anticancer effect of Tranilast against EC by antagonizing TRPV2, which is responsible for promoting EC tumorigenesis via the HSP70/27 and PI3K/Akt/mTOR pathways; the result also showed no off-target cytotoxicity, especially against non-tumor cells and tissues." (PMID 38336680, 2024). "Furthermore, GSVA and GSEA‐HALLMARKER analyses revealed that DCTN2 was positively associated with tumour‐promoting pathways such as the PI3K/AKT/mTOR pathway, MYC_targets, and E2F_targets, indicating that DCTN2 was significantly related to various tumour‐related pathways." (PMID 38842133, 2024). "Everolimus, an orally bioavailable mTOR inhibitor, was approved in 2013 for use in the treatment of TSC-related SEGAs and AMLs based on robust evidence from clinical trials demonstrating its efficacy in reducing tumor volume and delaying surgical interventions." (PMID 39727664, 2024).
tumor (continued). "Similarly, elevated mTOR levels in TNBC reinforce the pathway’s central role in promoting cellular metabolism and growth under nutrient-scarce conditions, which are common in the tumor microenvironment." (PMID 39850811, 2024). "Lenvatinib may inhibit tumor cell proliferation by downstream downregulation of PI3K, AKT and mTOR." (PMID 39333610, 2024). "The proliferation of tumor cells is primarily driven by TKRs, including members of the ERBB family (such as ERBB1/EGFR, ERBB2/HER2) and insulin-like IGF-1R, which activate oncogenic signalling pathways, including the PI3K/Akt/mTOR and MAPK/ERK pathways when overexpressed." (PMID 39199143, 2024). "Importantly, we found that LINC01605 promotes PDAC progression through mTOR signaling pathway activation, which further regulates cholesterol metabolism and thus leads to PDAC tumor growth and liver metastasis; we also found that it may interact with LIN28B." (PMID 39048994, 2024). "In addition, Deptor, as a tumor suppressor downstream of the PI3K/AKT/mTOR signaling pathway, inhibits AKT-induced protein synthesis, cell proliferation, and AKT pathway activation by blocking the mTOR signaling pathway." (PMID 39702468, 2024). "Then, we revealed that inactivation of the mTOR signaling pathway by everolimus not only attenuated the cell migration, proliferation and angiogenesis mediated by depletion of RNF26 in ccRCC cells but also abolished the ability of RNF26 to enhance tumor growth in vivo." (PMID 38890443, 2024). "As research on angiogenesis in tumor development progressed, treatment strategies targeting the vascular endothelial growth factor (VEGF) pathway emerged, along with a series of other approaches such as targeting the mammalian target of mTOR pathway (rapamycin) and immune checkpoint blockers." (PMID 38831470, 2024). "AMPK or mTOR may phosphorylate eEF2 in the absence of active eEF2K, ensuring that protein synthesis is finely modulated to promote tumor survival under adverse conditions." (PMID 39592671, 2024). "Having verified that NSUN4 can activate the mTOR signaling pathway, we utilized the CCK-8 experiment and colony formation assay to determine the impact of rapamycin on cell proliferation of cells to further clarify the molecular mechanism of NSUN4 in tumor promotion." (PMID 39634439, 2024). "Moreover, through in-depth exploration and in silico analysis of human MB tumor samples, we found a positive correlation between OTX2 and mTOR mRNA expression in three independent MB datasets (N = 952), emphasizing the clinical significance of OTX2’s regulatory impact on the mTORC2 pathway." (PMID 38674001, 2024). "Furthermore, the expression levels of autophagy-related markers (LC3 and LAMP1) were more increased in non-tumor tissues than in liver tumor tissues, but the expression levels of mTOR and MET were decreased in non-tumor tissues." (PMID 39519229, 2024). "In addition, quercetin induces tumor cell apoptosis, autophagy and reduces tumor cell viability mainly by reducing the stability of β-Catenin and HIF-1α, activating the expression of caspase 3 and inhibiting the phosphorylation of Akt, mTOR and ERK." (PMID 37685158, 2023). "It is not clear whether there is a link between alteration of the mTOR pathway and the site of origin of the primary tumour." (PMID 36980746, 2023). "Since inhibition of the AKT/mTOR pathway leads to downregulation of BRCA1/2 and homologous recombination and olaparib activates AKT/mTOR signaling, the combination of olaparib and ONC206 may have a synergistic effect in inhibiting tumor growth in EC via dual inhibition of the AKT/mTOR pathway." (PMID 37069726, 2023). "In addition, to evade the activation of feedback loops, the combination of dual inhibitors against PI3K and mTOR, as well as the simultaneous inhibition of the MAPK together with PI3K/mTOR signaling pathways, have shown efficacy in selected tumor types." (PMID 37566008, 2023).
tumor (continued). "Interestingly, PRPS1 mRNA expression is associated with reduced survival and positively correlated with DNA replication, tumor proliferation, and the PI3K/AKT/mTOR signature in the TCGA data set, confirming its broad essential role in cell growth and proliferation." (PMID 37909334, 2023). "GBM-initiating cells induce mTOR expression in microglia of mouse models, and the mTOR-mediated signaling of STAT3 and NF-κB contributes to the M2-like microglial phenotype, which hinders infiltration of effector T-cells, tumor proliferation, and immune responses." (PMID 37012233, 2023). "In addition, with the prolonged treatment of HepG2 cells with 20 μg/mL of the CXCL14 protein, the expression levels of pro-apoptotic genes BAK and BAX increased significantly, while the expression levels of tumor pro-proliferation genes HIF1A, mTOR and CDK1 decreased significantly." (PMID 37835641, 2023). "Because our study did not examine mTOR expression in skeleton muscle, a study examining mTOR in both skeletal and tumor tissue would provide important data on whether changes associated with PA for mTOR signaling in tumors are similar to those in muscle." (PMID 36895729, 2023). "One unexpected finding was that tumor initiation could be achieved in the absence of genomic alterations in the PI3K/AKT/mTOR signaling axis, given the extensive evidence implicating widespread mTOR activation in HNSC28,50–52." (PMID 37961717, 2023). "Meanwhile, AKR1B1 inhibition could block the mTOR pathway activation by activating 5′ adenosine monophosphate-activated protein kinase (AMPK) as it inhibits the phosphorylation of mTOR, Raptor, eIF4E, S6K, and 4E-BP1, thus inhibiting tumor growth." (PMID 37751590, 2023). "However, the significance of LAT1 in tumor aggressiveness, prognosis, and mTOR signaling has not yet been elucidated in CRC patients treated with post-operative adjuvant chemotherapy, including oxaliplatin." (PMID 36768934, 2023). "The mTOR pathway plays an important role in tumor formation and progress, but whether VC can have an anticancer effect on the mTOR pathway or not remains unclear." (PMID 36787291, 2023). "Similarly, RRM2B (nucleotide biosynthesis), PRKAA1 (AMPK signaling), and RICTOR (mTOR signaling) had widespread copy number gains exclusively in glycolytic cancers, apart from RRM2B, which had copy number gains in ~30% of evaluated PRAD patient tumor genes." (PMID 36831501, 2023). "The activation of PI3K/Akt/mTOR signaling also plays an important role in HNSCC chemotherapy and radiotherapy resistances, as the inhibition of the signaling pathway has shown positive effects on tumor proliferation and radiotherapy sensitization in preclinical studies." (PMID 37760799, 2023). "LXI-15029 can bind to mTOR proteins potently, significantly, or completely inhibiting the phosphorylation of the mTORC1 substrates S6K1 T389, S6 S235/236, and 4E-BP1 T70, as well as the phosphorylation of the mTORC2 substrate AKT S473, thereby inhibiting the growth of tumor cells." (PMID 38057772, 2023). "The mTOR signaling pathway is often activated in tumors, which not only regulates gene transcription, protein synthesis, cell proliferation, and immune cell differentiation, but also plays an important role in tumor metabolism." (PMID 37107564, 2023). "Oncogenic pathways including MYC, mTOR, WNT/β-Catenin and NOTCH were significantly enriched in tumor tissues, and pathways involved in stress response including unfolded protein response, DNA repair and UV response were also significantly enriched in tumor tissues." (PMID 37205121, 2023). "This is possibly because tumor cells that most downregulated MCL-1 via inhibition of mTOR pathway (AZD8055) in combination with navitoclax have undergone apoptosis (high levels of cleaved PARP and cleaved caspase 3) resulting in removal of dead cells from the tumor by phagocytosis." (PMID 37210412, 2023).
tumor (continued). "Furthermore, in the xenograft tumor model, the knockout methyltransferase G9a showed a concomitant marked reduction in H3K9 monomethylation and potent inhibition of mechanistic target of rapamycin (mTOR) expression and tumor growth." (PMID 37220590, 2023). "Furthermore, our results indicate that UQCRFS1 affects tumour cell proliferation, cell cycle, apoptosis, and DNA damage, which may be related to the AKT/mTOR signalling pathway." (PMID 37221238, 2023). "However, independent studies confirm that its expression in the MDA-MB-231 cell line not only favors tumor growth but also promotes the Warburg effect and induces resistance to paclitaxel and inhibitory molecules of the PI3K/AKT/mTOR pathway through activation of JAK2/STAT3." (PMID 36901916, 2023). "Interestingly, the probability of HCC recurrence after LT positively correlates with the mTOR pathway activity rate within the tumour rather than the peritumoral area." (PMID 37366904, 2023). "Preclinical models have also demonstrated that human epidermal growth factor receptor (EGFR) family inhibitors, SHP2 inhibitors, mammalian target of rapamycin (mTOR) inhibitors, and inhibition of CDK4/6 could enhance the anti-tumor activity of MRTX849 and inhibit KRAS-dependent signaling pathways." (PMID 37662925, 2023). "By acting on the TSC complex subunit 1 (TSC1)/TSC2 complex and the mechanistic target of rapamycin complex (mTOR) signal transduction, AKT might mediate a variety of cellular functions, including cell proliferation, differentiation, invasion, tumor angiogenesis, and metastasis 65-68." (PMID 36605482, 2023). "Quantitative analysis showed that tumor size and number was significantly reduced in mice treated with BEZ235 and IR than mice treated with either modality alone, further suggesting that inhibiting PI3K/AKT/mTOR pathway sensitized SCLC cells to radiation in vivo." (PMID 37802999, 2023). "Additionally, BTK knockdown and MALT1 knockout markedly impaired MCL tumor migration and dissemination, and MALT1 pharmacological inhibition decreased MCL cell viability, adhesion, and migration by suppressing NF-κB, PI3K/AKT/mTOR, and integrin signaling." (PMID 36719376, 2023). "To further explore the mechanisms underlying the suppressive effect of pharmacological VC on mTORC1 activation, we examined whether pharmacological VC inhibits mTOR through AMPK or MAPK, reported to be the mechanism mediating the tumor-killing properties of pharmacological VC." (PMID 36787291, 2023). "Furthermore, while verifying the related mechanism, we found a decrease in the protein level of Rictor in the pharmacological-VC-supplemented tumor samples, indicating the necessity of GSK3-FBXW7-induced Rictor degradation in the pharmacological-VC-dependent mTOR inactivation." (PMID 36787291, 2023). "The mTOR pathway expression is non-homogeneous across the tumour mass." (PMID 37366904, 2023). "mTOR plays a central role in gene transcription, cell apoptosis, proliferation and differentiation, angiogenesis, tumor formation and development, and cell senescence through PI3K/Akt/mTOR signaling pathway, and inhibiting this pathway could have therapeutic promises in leukemia disorders." (PMID 36909201, 2023). "Taken together, our data suggest that the global activation of the PI3K/AKT/mTOR signaling axis in tumors with short-term/lack of response to CDK4/6 inhibition in combination with ET extends beyond the tumor compartment into the surrounding tumor microenvironment." (PMID 36797347, 2023). "When activated, these tyrosine kinase receptors will activate either the PI3K/AKT/mTOR signaling pathway or the RAS/mitogen-activated protein kinase /extracellular signal-regulated kinase (RAS/MEK/ERK) pathway to increase the production of HIFs, thereby accelerating the growth of the tumor." (PMID 37176098, 2023).